PF4 (platelet factor 4)
Diseases named in the same sentence as PF4 in open-access papers (continued):
Sharing a sentence is not in itself a finding about the gene and the disease.
tumor (continued). "We propose the mechanism that the subsequent upregulation of PF-4 in platelets upon terminal differentiation of the megakaryocyte allows for the delivery of the elevated protein to the tumor, thereby suppressing tumor-dependant angiogenesis and promoting a dormant phenotype in the Lady mouse." (PMID 20525356, 2010). "Tumor growth and differentiation closely correlate with protein synthesis and degradation.We detected a significant increase of proteasome subunit alpha type 6, proteasome subunit alpha type 4 and 26S protease regulatory subunit S10B after PF4-DLR treatment." (PMID 21060779, 2010). "However, the downregulation of key angiogenic inhibitors such as thrombospondin-1 (THBS1) and platelet factor 4 (PF4) suggests a disrupted regulatory balance that may promote unchecked neovascularization within the tumor microenvironment." (PMID 40710368, 2025). "Furthermore, neutrophils stimulated by alhydrogel can inhibit tumor angiogenesis by releasing factors like platelet factor 4 and tumor necrosis factor-related apoptosis-inducing ligand (TRAIL), thus limiting blood and nutrient supply to the tumor and preventing its growth and spread." (PMID 39960903, 2025). "However, pulmonary megakaryocytes secrete platelet factor 4 (PF4), which in turn promotes hematopoietic function and megakaryocyte production under stress conditions caused by chemotherapy and radiotherapy, accelerating tumor growth." (PMID 38902986, 2024). "PF4 stimulates immune cancer surveillance and tumor inhibition by enhancing the adhesion of neutrophils, eosinophils, and monocytes and inhibiting the activation and proliferation of T cells, which decreases metastasis formation and tumor-platelet aggregates in animal models." (PMID 36926331, 2023). "In addition, platelets could secrete cellular growth factors such as platelet-derived growth factor, vascular endothelial growth factor, transforming growth factor-beta, and platelet factor 4 and then stimulate tumor angiogenesis and growth." (PMID 35028301, 2022). "Indeed Gr-1+CD11b+ cells expressed high levels of PF4 compared to 4T1 or B16F10 tumor cells." (PMID 27223426, 2017). "To understand the dynamics of PF4 expression in metastatic progression, we collected lungs from mice bearing 4T1 tumors at the premetastatic phase (day 5, 10 and 14) and the metastatic phase (day 21 and day 28) after tumor injection in the mammary fat pad (MFP)." (PMID 27223426, 2017). "We used Platelet Factor 4-DLR (PF4- DLR), a peptide derived by inserting DLR mutations into a PF4 47–70 aa fragment from Platelet Factor 4 that exhibits strong antiangiogenesis effects and that reduces angiogenesis and tumor growth in a dose-dependent manner in the U87-MG model." (PMID 22830012, 2012). "Platelets, being the endpoint of megakaryocyte differentiation, now carrying an increased load of PF-4, would later bind to the activated endothelium of the cancerous prostate where it would subsequently suppress the angiogenic drive induced by the developing tumor following its angiogenic switch." (PMID 20525356, 2010). "Platelets release proangiogenic and growth factors, including platelet factor 4 (PF4), platelet-derived growth factor (PDGF), and transforming growth factor-beta (TGF-β), all of which promote tumor progression." (PMID 40941629, 2025). "The expression of PF-4 and TPM3 was increased in cancer patients as compared to control individuals in the tumor tissue of the group of patients with comorbidities." (PMID 37176055, 2023). "Our analysis provides evidence that a combination of multi-omics features such as IL-8, PF-4, MLH-1, and specific plasma PS and PE lipids can help predict tumour progression in the early stages of CRC." (PMID 37731020, 2023). "In patients with comorbidities, the ANG-1, VEGF, PF-4, and TAC-1 genes clustered more closely in tumor tissue than in platelets (37.4% and 15.8% of the variance of PC1 and PC2)." (PMID 37176055, 2023).
tumor (continued). "In tumor tissue, an increased expression of VEGF, PFGF, ANG-1, PF-4, and LAMPTB4 was observed in the group of cancer patients without comorbidities, compared to healthy individuals without comorbidities." (PMID 37176055, 2023). "In the luminal A subtype, the variation in mRNA levels and overexpression of the VEGF, PDGF, ANG1, PF4, WASF3, and TPM3 genes coincided in both types of samples (platelets and tumor tissue, respectively)." (PMID 37176055, 2023). "Individually, it has been shown that binding of PF4 inhibits both FGF2 signaling and platelet activation, suppresses tumor growth and metastasis, and also induces apoptosis in myeloma cells." (PMID 34440575, 2021). "Some up-regulated genes including PPBP, OST4, PF4, GP1BB and CCL5 were related to tumor progression." (PMID 34722319, 2021). "Most tumor cells presented cytoplasmic and/or membranous staining patterns, except for VAP1, FABP4, PF4, and AGP, which occasionally displayed focal nuclear staining." (PMID 32224886, 2020). "Nevertheless, LCL-DOX inhibited statistically significant (by 40–60%) the expression of proteins involved in the anti-tumor response: TIMP-1, TIMP-2, IFN-γ, MIG, PF-4, and IL-12p70." (PMID 32340166, 2020). "The majority of each pro-angiogenic factor in the tumor (∼81% of VEGF and ∼50% of FGF2) is bound to the cell surface, while only a small percentage of the anti-angiogenic factors (∼16% of PF4 and ∼12% of TSP1) exists on the cell surface." (PMID 31379588, 2019). "In a tumor microenvironment with high HSPG, the release of PF4 in the tumor leads to an activation of VEGF signaling pathway." (PMID 31379588, 2019). "In the tumor with low HSPG level, the release of PF4 shows a stronger inhibition, particularly for unbound VEGF and the VEGFR2 and NRP1 complexes (blue line)." (PMID 31379588, 2019). "The secretion of PF4 and TSP1 leading to displacement of VEGF and FGF2 from HS binding sites is an important mechanism of tumor angiogenesis regulation." (PMID 31379588, 2019). "However, it remains to be elucidated whether PF4 has an impact on tumor metastasis." (PMID 27223426, 2017). "PF4 negatively regulates the PI3K-AKT/PKB signaling pathway and acts as a tumor-suppressor and hence, hypermethylated and repressed." (PMID 27461342, 2016). "KP drafted chapters "introduction", "PF-4 physiology and function CTAP-III physiology and function" and "Platelet regulation of tumor angiogenesis and tumor growth"; prepared tables and figures; formatted references." (PMID 23800319, 2013). "The following is a review of the role of PF-4 and CTAP-III in inhibition and regulation of tumor angiogenesis, respectively; results from rPF-4 clinical trial; and PF-4 and CTAP-III as cancer biomarkers." (PMID 23800319, 2013). "The effect of PF4-DLR and ILK1 siRNA on tumor angiogenesis was also evaluated by staining with anti-CD31 antibody." (PMID 21060779, 2010). "Mechanistically, HYW: Normalized tumor vasculature: Restored the balance between proangiogenic and antiangiogenic factors (reduced VEGFA/bFGF, increased TSP-1/PF4), enhanced pericyte coverage and improved vascular maturity, and enhanced intratumoral perfusion (ultrasound imaging)." (PMID 42238595, 2026). "PF4 is known to inhibit inflammation, angiogenesis, and tumor growth, although the mechanisms of PF4’s actions have not been fully elucidated." (PMID 41226302, 2025). "They play a crucial role in tumor growth and metastasis, with key mechanisms involving immunosuppression and tumor cell survival influenced by PLT α‐granule components, such as TGF‐β1 (transforming growth factor‐β1) and PLT factor 4 (PF4)." (PMID 40512151, 2025). "CAFs contribute to ECM production by secreting CXCL16 and enhancing MMP expression, which increases tumor stiffness and alters ECM structure.The binding of PF4/CXCL4 and PPBP/CXCL7 to CXCL12, mediated by G protein-coupled receptors, promotes EMT and the expression of chemokines and cytokines." (PMID 40038745, 2025).
tumor (continued). "Platelet factor 4 (PF-4/CXCL4) and connective tissue-activating peptide III (CTAP-III) are two platelet-related chemokines which regulate tumor angiogenesis and inflammation in the tumor microenvironment, thereby regulating tumor growth." (PMID 38372784, 2024). "Moreover, in tumor tissue from patients with comorbidities, there was an increase in the gene expression of TPM3 and PF4." (PMID 37176055, 2023). "Although useful in cancer diagnosis, the exact mechanisms of transition of platelets to the TEP phenotype are unclear but appear to involve the systemic exchange of platelet- and tumor-derived biomolecules, possibly implying their involvement with TME-derived PF4." (PMID 37569299, 2023). "In addition, activated platelets release PF4, which increases the levels of macrophage nuclear factor-kappa B (NF-κB), promotes MMP-9 gene transcription, and facilitates tumor vascular remodeling." (PMID 37153586, 2023). "Some of the chemokines, including the platelet factor 4 (PF4), the C-X-C motif chemokine ligand 9 (CXCL9), and CXCL10, may inhibit tumor vessel formation." (PMID 38001676, 2023). "Notably, there was a positive association between the levels of ARGs and CNV alteration; for example, the expression levels of PRG2, SERPINA5, and THBD were low in tumor tissues, while VEGFA, PF4, and PTK2 were expressed at high levels." (PMID 37938164, 2023). "Tumor cells also recruit platelets into the tumor microenvironment (TME), and platelets are activated by tumor cells to release the cytokines VEGF, CCL5, PDGF, TGFβ, PG, TPM3, LPA, PF4, PAF, and HGF, which promote the epithelial-mesenchymal transition of tumor cells." (PMID 35836573, 2022). "Therefore, we tested a specific role for platelet miRNAs in tumor cell apoptosis in vivo, by comparing cleaved Caspase-3 enrichment in lysates of ectopic KPC tumors resected from Dicer1fl/fl/Pf4-Cre mice versus from control mice." (PMID 34936674, 2021). "Moreover, it inhibits tumor growth and angiogenesis as it can bind to different proteins such as growth factors and cytokines like FGF, VEGF, PF4, IL8, and adhesion proteins such as vitronectin, fibronectin, selectins, and integrins." (PMID 34440575, 2021). "Our results are in line with the previous study in the absence of platelets, showing that PF4 suppresses tumor growth and metastasis." (PMID 34440575, 2021). "Tumor mass differences at d10 post-implantation showed a trend toward higher tumor mass in the Dicer1fl/fl/Pf4-Cre mice, but this difference was not significant." (PMID 34936674, 2021). "The activated platelets facilitate tumor cell proliferation by secreting a number of angiogenic tumor growth factors, such as thrombopoietin (TPO), platelet factor 4 (PF4), transforming growth factor beta (TGFb), vascular endothelial growth factor (VEGF) and platelet-derived growth factor (PDGF)." (PMID 32867390, 2020). "Further to sustained and elevated PF4 levels observed at day 120, PF4 was also significantly increased at day 19, where mice bore only microscopic, non-palpable, and non-angiogenic tumours." (PMID 31722230, 2020). "Particularly, platelet factor 4 (PF4) or CXCL4, a member of CXC chemokine family, acts as an angiogenesis inhibitor which may contribute to prevent tumor metastasis." (PMID 33182810, 2020). "Lastly, we apply the model to simulate a controlled release of PF4 in tumor tissue, and our results indicate that the HSPG level in the tumor microenvironment might affect the response to platelet activation and recombinant PF4 anti-angiogenic therapy." (PMID 31379588, 2019). "In addition to affecting the VEGF signaling complexes, release of PF4 influences the FGF2 signaling complexes to different extents, depending on the tumor microenvironment." (PMID 31379588, 2019). "Interestingly, varying PF4 secretion can significantly elevate the levels of unbound FGF2 and unbound VEGF in tumor tissue." (PMID 31379588, 2019).
tumor (continued). "To better understand the effects of targeting angiogenic factors in the tumor, we built a new tissue-based systems biology model characterizing the extracellular network that involves four main angiogenic factors regulating tumor angiogenesis, including VEGF, FGF2, TSP1, and PF4." (PMID 31379588, 2019). "Similarly, the Platelet Factor 4 (PF4) can also up-regulate SOCS3 expression leading to the inhibition of STAT3, Th17 differentiation and tumor growth." (PMID 31480382, 2019). "To investigate whether the decreased PF4 in the premetastatic lung was tumor model specific, we examined PF4 expression in the B16F10 tumor model, where premetastatic lung was defined as 18 days after tumor inoculation." (PMID 27223426, 2017). "Our studies show that PF4, but not the other family members, is produced in myeloid cells in premetastatic lungs of normal mice and early stage of tumor-bearing mice." (PMID 27223426, 2017). "However, growth factors, including platelet-derived growth factor, platelet factor 4 and TGF-β generated by platelets, can promote the proliferation and invasion of tumor cells." (PMID 29383181, 2017). "PF-4 and CTAP-III can be used as biomarkers of tumor growth." (PMID 23800319, 2013). "We have summarized emerging data on role of PF-4 and CTAP-III in regulation of tumor growth." (PMID 23800319, 2013). "Reports on the ability of PF-4 to stimulate innate immune response predominate suggesting that rather than using inflammation to stimulate tumor growth, PF-4 stimulates immune cancer surveillance and tumor inhibition." (PMID 23800319, 2013). "Inhibitory effect of recombinant PF-4 on tumor growth and metastasis is most likely consequence of tumor angiogenesis inhibition, because PF-4 does not inhibit proliferation of tumor cells in vitro." (PMID 23800319, 2013). "KG drafted chapters "PF-4 and CTAP-III as biomarkers of tumor growth"." (PMID 23800319, 2013). "Interestingly, treatment with PF4-DLR and an anti-ILK1 siRNA resulted in decreased tumor mass and a reduction in the number of tumor vessels." (PMID 22830012, 2012). "PF4 inhibits the functions of two potent proangiogenic factors, FGF and VEGF, that actively recruit circulating endothelial cells to form new blood vessels in the tumor." (PMID 21693026, 2011). "A high platelet count tends to induce an aggregation of tumor cells by releasing biological factors; assist in stimulating the development of new blood vessels through interactions with PDGF, VEGF, and PF4; and activate DNA damage promoters, which may contribute to carcinogenesis." (PMID 39403327, 2024). "The expression levels of ccl-2 (MCP-1), ccl-20 (MIP-3), ccl-7 (MCP-3), CXCL-4 (PF-4), CXCL 1 (Gro -), and CXCL-12 (SDF-1) are also significantly increased in replicative senescent cells, allowing the disruption of the blood-tumor barrier integrity and greater spread of tumor cells." (PMID 37450933, 2024). "In addition, a co-expression pattern was identified for PF4/CXCR3 between ductal cells and T cells in PT tissues, suggesting a potential mechanism by which CXCR3+ T cells could be recruited to the tumor epithelium." (PMID 37612267, 2023). "Only in tumor tissue were PF4 and LAPTM4B significantly increased without comorbidities." (PMID 37176055, 2023). "Tumor infiltration of leukocytes/lymphocytes was unaltered by host platelet miRNA deletion; however, we cannot completely rule out potential direct or indirect effects of Pf4-Cre-mediated Dicer1 deletion in blood cells in addition to platelets." (PMID 34936674, 2021). "Distributions of leukocytes/lymphocytes, identified by Cd45/Cd16/Cd3 staining, appeared similar in the tumors in Dicer1fl/fl/Pf4-Cre and Pf4-Cre mice, indicating that the decreased levels of circulating leukocytes/lymphocytes did not alter their enrichment in the tumor microenvironment." (PMID 34936674, 2021).
tumor (continued). "Interestingly, PF4 was produced in Ly6G+CD11b+ cells from lungs of non-tumor bearing mice, and gradually decreased during tumor progression, at both mRNA and protein levels." (PMID 27223426, 2017). "Similarly, the same targeting peptide that enhances IL12 therapies in one model fails to improve the effect of either IL15 or PF4 for inhibiting tumor growth in the same model." (PMID 24369443, 2013). "We identified 24 proteins that were differentially expressed in the tumors treated with PF4-DLR for 10 days (14 up-regulated and 10 down-regulated), some of which are known to be involved in tumor development, and may constitute potential prognostic markers or therapeutic targets." (PMID 21060779, 2010). "In addition, PF4 and PPBP may function as tumor suppressors in cirrhotic HCC, meanwhile, CCL19 may act as a protective factor in non-cirrhotic HCC, while miRNAs regulate mechanisms still unclear, further experimental trials are still need to be launched in the future." (PMID 31346321, 2019). "Finally, PF-4 is a locally acting protein whose role is to modulate the stroma of the wound or the tumor and its systemic administration may not ensure its bioavailability within the respective microenvironment." (PMID 23800319, 2013). "A selection of the proteins from this panel are of high abundance in plasma (i.e., C3 and SERPINA1), while others are not (i.e., PF4 and ECM1), and so reflect the contributions of localized changes due to tumor presence and anti-tumor immunity." (PMID 35008327, 2021). "Of note, platelet factor 4 (PF4), a pro-angiogenic protein, was found in the platelets of mice bearing LPS tumours at 120 days post-implantation and not in non-tumour-bearing mice." (PMID 31722230, 2020). "The C8 cluster prevalent on the tumor periphery of rIL7-treated tumors exhibited the highest T cell, macrophage, and DC signatures and expressed higher levels of MHC class II (H2-Aa and H2-Eb1) and Pf4 genes rather than Arg1 genes." (PMID 38424167, 2024).